SCARNA18 (small Cajal body-specific RNA 18)
Synonyms: U109; SCARNA18A
Gene: Small nucleolar RNA gene on chromosome 5 (83,064,204 to 83,064,337, reverse strand). Ensembl gene ENSG00000238835.
Gene Ontology:
Biological process: RNA processing
Cellular component: nucleolus
Homologues: Orthologues: chimpanzee SCARNA18 (99% identical), macaque SCARNA18 (96% identical), pig SCARNA18 (90% identical), guinea pig SCARNA18 (84% identical), rat Scarna18 (83% identical), mouse Gm24507 (82% identical). Paralogues in human: SCARNA18B (89% identical).